FFAR2 (free fatty acid receptor 2)
Diseases named in the same sentence as FFAR2 in open-access papers (continued):
Sharing a sentence is not in itself a finding about the gene and the disease.
infection (26 papers, 2015 to 2025). The state of being infected such as from the introduction of a foreign agent such as serum, vaccine, antigenic substance or organism. "In supernatants of both in vitro cell lines A549 WT and FFAR2-KO, infection with IAV resulted in a significant upregulation of IP-10 after 24 h of infection." (PMID 40745568, 2025). "In line with this, gB498-505-specific CD8+ T cells were lodged into the skin of WT and Ffar2–/–;Ffar3–/– mice by day 9 post-infection." (PMID 38524121, 2024). "We summarize recent advances in understanding the role of SCFAs and FFAR2 in various infection types and propose the manipulation of this receptor as an additional therapeutic strategy to fight infections." (PMID 34926327, 2021). "Although increased concentrations of SCFAs, especially acetate, are observed in various types of infections, little is known about the role of SCFAs and FFAR2 during infectious diseases." (PMID 34926327, 2021). "Combined with high expression in neutrophils, this upregulation strongly implies an involvement of FFAR2 and SCFAs in infection control." (PMID 34926327, 2021). "Intriguingly, activation of FFAR2 by SCFA administration, especially acetate, diminishes the susceptibility toward various types of infections caused by bacteria and viruses." (PMID 34926327, 2021). "More recently, some research groups have investigated the role of FFAR2 in infections in more detail using FFAR2 knockout mice or FFAR2 inhibitors." (PMID 34926327, 2021). "Strikingly, 46- and 14-fold decreases in virus titers were observed at 24 and 48 h p.i., respectively, in Ffar2 siRNA-treated RAW 264.7 cells infected with AH05 (H5N1) virus at a multiplicity of infection (MOI) of 0.1." (PMID 31694949, 2020). "We revealed that FFAR2 facilitates the internalization of IAV into target cells during the early stage of infection." (PMID 31694949, 2020). "The best described and established effector function of FFAR2 activation in neutrophils is the induction of chemotaxis toward local sites of infection or inflammation, whereas the effect on other neutrophil functions, such as the release of cytokines, is less clear." (PMID 34926327, 2021). "Thus, our immune system appears to be able to use FFAR2-dependent detection of SCFAs for perceiving and even averting severe infections." (PMID 34926327, 2021). "In 2003, Le Poul proposed a role of FFAR2 in infection control." (PMID 34926327, 2021). "Although a general activation of FFAR2 might be useful to fight infections, it could have multiple side effects due to the implication of FFAR2 in other physiological processes, including metabolic and brain functions." (PMID 34926327, 2021). "Also, a recent study demonstrated the role of short-chain fatty acids (SCFAs), in particular acetate, in ameliorating the infection by activating the free fatty acid receptor 2 (FFAR2) on ILC3s and neutrophils." (PMID 34804991, 2021). "In Huh7 cells, increased expression of acute-phase proteins, such as C-reactive protein and serum amyloid A1, was observed with the progression of infection, whereas FFAR2 and STEAP4 with metalloreductase activity showed significantly higher upregulation than other genes." (PMID 34899651, 2021). "FFAR2 is important for infection by different subtypes of IAV." (PMID 31694949, 2020). "To assess the impact of the production of IP-10 on the reduced viral titer detected in A549 WT cells, absent in FFAR2 deficient cells, we repeated the same experimental set-up with infection in combination with acetate treatment on IP-10 deficient cells (IP-10-KO)." (PMID 40745568, 2025). "Therefore, FFAR2 modulation by synthetic or even natural ligands could be a beneficial therapeutic option for improved infection control." (PMID 34926327, 2021). "To analyze the effect of acetate and FFAR2 in the pulmonary epithelial cells during IAV infection, we repeated the stimulation and infection setup using A549 cells with a global knock-out of FFAR2 (FFAR2-KO)." (PMID 40745568, 2025).
infection (continued). "Multiple host restriction factors, such as transport protein particle complex 6A (TRAPPC6A), phospholipid scramblase 1 (PLSCR1), free fatty acid receptor 2 (FFAR2), inhibit IAV replication at various infection stages through such interactions." (PMID 41463543, 2025). "To corroborate this finding, we visualized the cellular distribution of NP by means of confocal microscopy in both FFAR2-knocked-down and control A549 cells infected with AH05 (H5N1) virus at early time points of infection." (PMID 31694949, 2020). "This antiviral effect was absent in A549 cells lacking either FFAR2 or the key interferon response mediator IP-10, suggesting both are essential for acetates mechanism during infection." (PMID 40745568, 2025). "Additionally, acetate has been shown to ablate infection with rhinovirus (RV) and respiratory syncytial virus (RSV) in mouse models by upregulating a free fatty acid receptor 2 (FFAR2), which induced a type 1 interferon (IFN) response by RIG-I." (PMID 37515117, 2023). "Further investigation on the relationship of FFAR2 and FFAR4 is warranted and may yield a greater understanding of how these two receptors may impact one another, as well as their combined phenotypic alterations to epithelial and immune cells during infection or other diseased states." (PMID 37515117, 2023).
metabolic disorders (23 papers, 2012 to 2026). "So far, the adipocyte-specific effect of FFAR2 on glucose homeostasis and metabolic disorders is inconsistent and inconclusive." (PMID 37484954, 2023). "GPR43 (free fatty acid receptor 2) is known to regulate energy balance in the host through the gastrointestinal and adipose tissues, and is being explored as a potential therapeutic alternative for metabolic diseases." (PMID 35889107, 2022). "Hence, this compound warrants further exploration in the context of developing new FFAR2 agonists as potential treatments of inflammatory and metabolic diseases." (PMID 34195966, 2022). "Both FFAR1 and FFAR2 have been suggested to act as receptors for long-chain fatty acids and play important roles in various physiological and pathological processes, including metabolic disorders." (PMID 34445796, 2021).
bacterial infection (7 papers, 2018 to 2025). "A recent study in Cell Reports revealed that short chain fatty acids in the gut and blood can regulate macrophages to suppress bacterial infection by activating free fatty acid receptor 2 (FFAR2)." (PMID 33691643, 2021). "Another group additionally demonstrated the importance of the GPCR free fatty acid receptor 2 (Ffar2) in protection from bacterial infection." (PMID 32887435, 2020). "In particular, we identified that FFAR2+TNFAIP6+ NEUs and THBS1+IL1B+ MOs undertook an important role in the immune response to bacterial infection." (PMID 36119025, 2022). "Considering the CSF cell compositions, the CSF in the refractory stage contained fewer FFAR2+TNFAIP6+ NEUs and THBS1+IL1B+ MOs, which indicated that an immune response to a bacterial infection was not the main reaction to this condition." (PMID 36119025, 2022).
intestinal diseases (7 papers, 2016 to 2025). "We established that SCFA-mediated GLP-1 secretion requires the presence of FFAR 2/3 signalling; therefore, it is unlikely that a fiber-free diet induces a decrease in luminal SCFAs and sensitivity to intestinal disease involves the SCFA-FFAR2/3-GLP-1 pathway." (PMID 39057718, 2024).
adenocarcinoma (4 papers, 2016 to 2024). A common cancer characterized by the presence of malignant glandular cells. "The function of human and mouse FFAR2 and FFAR3 was also investigated via heterologous expression in human adenocarcinoma lung alveolar basal epithelial cell line, A549 (which has low endogenous levels of FFAR2 and FFAR3 [data not shown])." (PMID 27667443, 2016).
kidney disease (4 papers, 2021 to 2026). "Additionally, the FFAR2 specific allosteric agonist CFMB had decreasing effects on TNF-α-induced MCP-1 upregulation in cortical epithelial cells, indicating an anti-inflammatory effect of FFA2 and FFA3 receptor signaling in renal diseases." (PMID 33578942, 2021).
infectious disease (1 paper, 2021). A disorder directly resulting from the presence and activity of a microbial, viral, or parasitic agent in humans. "In summary, all of these different findings suggest a relevant role of changing SCFA concentrations and FFAR2 during human infectious diseases." (PMID 34926327, 2021). "In addition to these results, which are based on mouse studies, the first clinical observations propose an involvement of FFAR2 in human infectious diseases, as outlined in the next section." (PMID 34926327, 2021). "The idea of manipulating FFAR2 during an infectious disease is quite intriguing." (PMID 34926327, 2021).
neurodegenerative disease (1 paper, 2023). A disorder of the central nervous system characterized by gradual and progressive loss of neural tissue and neurologic function. "Therefore, we hypothesize that Cd is implicated in the mechanism of neurodevelopmental toxicity through the gut–brain axis, demonstrating that FFAR2 might be a new potential target for the treatment of neurodevelopmental toxicity and neurodegenerative diseases." (PMID 37233698, 2023).
neurological diseases (1 paper, 2023). "Notably, FFAR2 expression may be associated with neurotoxicity and may be involved in brain development and neuronal differentiation as a potential drug target against several neurological diseases." (PMID 37233698, 2023).
FFAR2 also shares sentences with these, for which no sentence is quoted: Arthritis (35 papers); type 2 diabetes (13); ulcerative colitis (8); inflammation (7); cardiovascular diseases (6); psoriasis (6); bacterial pneumonia (4); atrial fibrillation (3); autoimmune disease (3); cardiac hypertrophy (3); chronic kidney disease (3); Constipation (3); periodontitis (3); prostate carcinoma (3); adenoma (2); allergic asthma (2); Anxiety (2); atopic dermatitis (2); colon polyps (2); enteritis (2); food allergies (2); hepatocellular carcinoma (2); hyperlipidemia (2); immune diseases (2); kidney damage (2); liver fibrosis (2); Lung Injury (2); pneumococcal infection (2); renal fibrosis (2); respiratory syncytial virus infection (2).
A further 65 diseases each share a sentence with FFAR2 in 2 papers or fewer.